PTH (parathyroid hormone)
Diseases named in the same sentence as PTH in open-access papers (continued):
Sharing a sentence is not in itself a finding about the gene and the disease.
Hypocalcemia (continued). "This study aimed to investigate the utility of measuring parathyroid hormone (PTH) levels as a predictor of hypocalcemia in a population of patients undergoing total thyroidectomy for thyroid cancer between 2016 and 2019." (PMID 40091995, 2025). "While many studies focus on its effectiveness in locating parathyroid glands during surgery, there is a lack of data on its impact on short‐term, mid‐term, and long‐term calcium (hypocalcemia) and parathyroid hormone (PTH) levels after surgery." (PMID 40550518, 2025). "One patient presented with asymptomatic hypocalcemia with a total calcium level of 7.2 mg/dL and a low PTH level of 5.0 pg/mL (normal range, 10 − 65 pg/mL) and was consequently diagnosed with hypoparathyroidism." (PMID 40382647, 2025). "provided a predictive model combined of preoperative PTH, serum calcium, and ALP levels for the risk of severe hypocalcemia after PTX, and advocated for increased calcium supplementation in high-risk group of patients." (PMID 41367906, 2025). "Hypocalcemia is the most common postoperative complication, typically resulting from the abrupt decline in PTH levels following gland excision." (PMID 40710393, 2025). "Heexperienced persistent hypocalcemia until October 2011, when PTH and calciumlevels increased again." (PMID 40893023, 2025). "Laboratory investigations revealed hypocalcemia, hyperphosphatemia, and elevated serum PTH, with normal serum magnesium, renal function, and vitamin D levels, suggestive of PTH resistance." (PMID 41170251, 2025). "Nevertheless, the constellation of hypocalcemia, hyperphosphatemia, and elevated PTH with normal renal function strongly supports PHP type 1B as the most likely diagnosis in this context." (PMID 41322012, 2025). "Intraoperative PTH monitoring has been increasingly used in recent years to predict hypocalcemia after TT." (PMID 40786097, 2025). "Patients often present with chronic hyperphosphatemia, elevated parathyroid hormone (PTH) levels, and, in some cases, hypocalcemia." (PMID 39982237, 2025). "Vitamin D and phosphate metabolism is classically under the control of parathyroid hormone (PTH) which is produced by parathyroid glands mainly following hypocalcemia, i.e. low Ca2+ serum concentration." (PMID 39887469, 2025). "High preoperative alkaline phosphatase (ALP), low preoperative corrected calcium, high preoperative parathyroid (PTH), and younger age were shown to be significantly higher in patients who developed hypocalcemia after parathyroidectomy." (PMID 40517023, 2025). "The best cutoff value of the decrease of ioPTH level between PTH assessed after induction of anesthesia and at 10 min after completion of surgery for predicting hypocalcemia was evaluated." (PMID 39888415, 2025). "In this setting, impaired phosphate excretion, reduced vitamin D activation, and hypocalcemia stimulate a compensatory overproduction of PTH." (PMID 40710393, 2025). "Treatment for prevention of hypocalcemia was started depending on early measurement of serum PTH level." (PMID 40205289, 2025). "Secondary HPT is the elevation of parathyroid hormone (PTH) in response to hypocalcaemia induced by phosphate retention and reduced calcitriol synthesis as a consequence of reduced renal function." (PMID 40455298, 2025). "Hypomagnesemia can induce hypocalcemia due to functional hypoparathyroidism, as parathyroid hormone (PTH) secretion is magnesium-dependent." (PMID 41246742, 2025). "Laboratory findings revealed severe hypocalcemia (1.28 mmol/L), normophosphatemia (1.36 mmol/L), and low intact parathyroid hormone levels (0.84 pmol/L)." (PMID 40655406, 2025). "Hypocalcaemia is known to induce secretion of parathyroid hormone (PTH) in the parathyroid glands, which affects the renal handling of phosphate, further decreasing the levels of phosphate in serum." (PMID 39306590, 2025).
Hypocalcemia (continued). "Through retrospective comparative analysis, this study aims to assess the effect of intraoperative topical application of papaverine on the incidence of hypocalcemia and HP after total thyroidectomy, as well as on PTH recovery." (PMID 41356014, 2025). "Treatment-resistant hypocalcaemia requiring escalation to alfacalcidol, along with elevated PTH and an extensive calcification pattern, strongly supports end-organ resistance rather than simple deficiency states." (PMID 41322841, 2025). "Although overall hypocalcaemia rates were similar across groups, PTH-driven selective supplementation alone had significantly more symptomatic cases." (PMID 41229353, 2025). "PTH has been described in the medical literature as a paraclinical study serving as a predictor of hypocalcemia after thyroidectomies." (PMID 40091995, 2025). "If the patient is being carefully watched, the phase of hypocalcemia and hyperphosphatemia that will later trigger the secretion of PTH needs immediate and specific intervention." (PMID 41301699, 2025). "Postoperatively, patients were assessed on the basis of serum total calcium, ionized calcium, serum PTH, and simultaneous clinical evaluation for symptoms of hypocalcemia." (PMID 39996189, 2025). "Laboratory values that support postoperative hypocalcemia include reduced serum ionized calcium and PTH levels." (PMID 40225429, 2025). "During these episodes, she was found to have severe hypocalcemia and hyperphosphatemia, but with normal to mildly elevated serum PTH levels ranging from 45 pg/ml to 72 pg/ml (nl 9-72)." (PMID 40904804, 2025). "Nevertheless, PTH decreased dramatically after PTx in most cases and some authors reported calcium and vitamin D analog administration for correcting hypocalcemia, similar to our case." (PMID 40149691, 2025). "Hypoparathyroidism is a rare disease characterized by hypocalcemia and relatively high phosphate levels due to low parathyroid hormone (PTH) levels." (PMID 40869557, 2025). "Persistent hypocalcemia and hypophosphatemia that develop as a consequence of comprehensive re‐mineralisation of the skeletal system after PTH suppression are considered a critical complications of parathyroidectomy." (PMID 40517023, 2025). "The identification of autoimmune hypoparathyroidism is a diagnostic challenge mainly based on clinical criteria of low PTH levels along with hypocalcemia and hyperphosphatemia as were described in all reported cases, including ours." (PMID 40356787, 2025). "Successful PTx often translates into reduced bone turnover and mineralization and severe hypocalcemia due to sudden drop in serum PTH." (PMID 40149691, 2025). "The manifestation of the disease is hypocalcemia and hyperphosphatemia of varying severity, despite inadequately elevated levels of PTH." (PMID 40444234, 2025). "The parathyroid gland will detect hypocalcemia via receptors in the membrane and rapidly release parathyroid hormone." (PMID 40689000, 2025). "PTH levels remain a common predictor of hypocalcemia after TT, reliance solely on PTH has limitations." (PMID 40786097, 2025). "Concomitant hyperphosphatemia, reduced renal 1 alpha hydroxylase (CYP27B1) activity, and hypocalcemia (secondary to low calcitriol) are directly responsible for the increased release of PTH, leading to SHPT." (PMID 40077644, 2025). "This resistance to PTH results in hypocalcemia, hyperphosphatemia, and secondary hyperparathyroidism." (PMID 40893942, 2025). "In these ways, PTH orchestrates a multi-organ response to hypocalcemia: extracting calcium from bone, conserving urinary calcium (and dumping phosphate) in the kidney, and increasing intestinal calcium uptake via enhanced vitamin D activation." (PMID 41227247, 2025). "Hypocalcemia triggers the increased secretion of parathyroid hormone (PTH), which enhances renal phosphate excretion, leading to further declines in the serum phosphate levels." (PMID 40218268, 2025).
Hypocalcemia (continued). "To further assess the predictive value of PTH levels in detecting postoperative hypocalcemia, we performed an ROC curve analysis." (PMID 40091995, 2025). "While previous studies have assessed PTH at two, four, or six hours postoperatively, our study evaluates 24-hour PTH levels as a predictor of hypocalcemia." (PMID 40091995, 2025). "ADH1 and ADH2 are characterized by hypocalcemia, hyperphosphatemia, and normal or inappropriately low levels of circulating PTH." (PMID 39658204, 2025). "In this instance, we have observed persistent hypocalcemia, hyperphosphatemia, and elevated PTH despite vitamin D repletion." (PMID 41181744, 2025). "Mg2+ depletion impairs parathyroid hormone (PTH) secretion and renal tubules and bone are resistant to PTH action, resulting in hypocalcemia." (PMID 40248148, 2025). "Hypomagnesemia also leads to hypocalcemia by blunting parathyroid hormone (PTH) secretion and inducing end-organ PTH resistance." (PMID 40271332, 2025). "In PHP, these mechanisms are disrupted, leading to hypocalcemia and hyperphosphatemia, despite elevated PTH." (PMID 41170251, 2025). "Post-operatively, the hypocalcaemia-related symptoms resolved, and the serum calcium and PTH levels normalized." (PMID 41473619, 2025). "Prolonged stimulation of the parathyroid glands by factors such as hypocalcemia and hyperphosphatemia can lead to excessive secretion of PTH, resulting in secondary hyperparathyroidism." (PMID 40810070, 2025). "Key findings included severe hypocalcemia, elevated alkaline phosphatase and parathyroid hormone levels, normal or elevated 25(OH)D, and high RSSs." (PMID 40218268, 2025). "The aim of this study is to analyze PTH levels as predictors of hypocalcemia in patients undergoing total thyroidectomy for thyroid cancer at a tertiary hospital in Ecuador, within a cohort studied from 2016 to 2019." (PMID 40091995, 2025). "Regular monitoring of serum calcium levels is essential, with PTH measurements recommended in the presence of hypocalcemia to facilitate early diagnosis and appropriate management." (PMID 40590356, 2025). "The ROC curve illustrates the relationship between sensitivity and 1-specificity, with an area under the curve (AUC) of 0.54, indicating a modest predictive ability of PTH levels for hypocalcemia." (PMID 40091995, 2025). "PTH resistance is the hallmark of pseudohypoparathyroidism (PHP), resulting in hypocalcemia and hyperphosphatemia due to impaired cAMP-dependent signaling mediated by the Gsα protein." (PMID 40125101, 2025). "Hypocalcemia after parathyroidectomy was attributed to the rapid skeletal uptake of calcium as a result of a sudden decline in the highly elevated PTH levels." (PMID 40517023, 2025). "In secondary hyperparathyroidism (SHPT), typically seen in chronic kidney disease (CKD), the stimulus for excess PTH is sustained hypocalcemia due to impaired phosphate excretion and low vitamin D levels." (PMID 41211056, 2025). "Investigations revealed severe hypocalcemia with inappropriately low PTH, favoring the diagnosis of hypoparathyroidism along with vitamin D deficiency and high creatinine phosphokinase." (PMID 40717880, 2025). "In cases of moderate or severe hypomagnesemia, both PTH levels and renal calciumreabsorption decrease, resulting in hypocalcemia." (PMID 41370665, 2025). "The PTH levels were inappropriately normal with hypocalcemia, also reported as a rare occurrence by others in case reports, likely due to impaired PTH secretion and resistance from hypomagnesemia." (PMID 40492015, 2025). "Autosomal Dominant Hypocalcemia type 1 (ADH1), caused by gain-of-function variants in the calcium-sensing receptor (CASR), is characterized by a variable degree of hypocalcemia and hypercalciuria with inappropriately low PTH." (PMID 39607645, 2025).
Hypocalcemia (continued). "The frequency of hypocalcemia in response to multiple daily PTH injections and PTH pump therapy was lower than the frequency of hypocalcemia in response to single daily PTH injections (not statistically significant difference)." (PMID 40177730, 2025). "Magnesium’s role in calcium metabolism can lead to hypocalcemia due to hypoparathyroidism, resistance to parathyroid hormone (PTH), and the decreased synthesis of calcitriol." (PMID 40868117, 2025). "We conducted an observational, analytical, descriptive, cross-sectional investigation, assessing PTH levels as a predictor of hypocalcemia following thyroidectomy." (PMID 40091995, 2025). "During this period, the sudden reduction in PTH stimulation of bone resorption and increased maturation of inchoate osteoblasts can lead to unopposed mineral apposition resulting in hypocalcaemia, known as the hungry bone syndrome (HBS)." (PMID 40670910, 2025). "BMD originates from reduced 1,25-dihydroxy vitamin D and hypocalcemia, which lead to secondary hyperparathyroidism, with increased parathyroid hormone (PTH) levels and hyperphosphatemia as the progression of renal damage." (PMID 40045219, 2025). "Elevated levels of PTH pre-operatively, with a cutoff of over 166 pmol/L, are a powerful predictor of post-operative hypocalcemia and require higher doses of replacement." (PMID 41301699, 2025). "Perioperative PTH levels have been used to determine the effectiveness of PT in patients with hyperparathyroidism and to predict postoperative hypocalcemia in patients after total or near‐TT." (PMID 39831132, 2025). "Most notably, when serum calcium levels drop below the normal range (hypocalcemia), the parathyroid glands release parathyroid hormone (PTH), which upregulates osteoclast differentiation and activity to liberate calcium from the bone mineral matrix." (PMID 40710319, 2025). "The biochemical findings showed severe hypocalcemia, normal or mildly low serum phosphate, elevated alkaline phosphatase and parathyroid hormone levels, and normal serum 25-hydroxyvitamin D levels." (PMID 40218268, 2025). "Hypoparathyroidism, a rare metabolic disorder characterized by hypocalcemia, hyperphosphatemia, and low PTH level, is the most commonly identified etiologic condition associated with the development of Fahr’s syndrome." (PMID 40070612, 2025). "In regard to treatment of hypocalcemia, ChatGPT included recombinant PTH as a potential option, which the reviewers pointed out was not available in the United States at the time of this study following a safety-related recall in 2019." (PMID 39881674, 2025). "The persistent elevation of PTH levels indicates secondary hyperparathyroidism, a compensatory response to hypocalcemia." (PMID 40218268, 2025). "Conversely, in AKI, higher PTH concentrations are primarily driven by hypocalcemia and decreased vitamin D levels, which stimulate the parathyroid glands to secrete PTH." (PMID 40005891, 2025). "Biochemical profiling revealed universal hypocalcemia and hypoparathyroidism (reduced serum calcium and PTH levels), accompanied by decreased 25-hydroxyvitamin D3 (seven cases) and hyperphosphatemia (six cases)." (PMID 40590356, 2025). "If the surgery involves them, it will impact parathyroid hormone secretion, leading to reduced blood calcium levels and inducing hypocalcemia symptoms such as cramps in the hands and feet, potentially resulting in lasting damage that affects quality of life." (PMID 40791984, 2025). "Hypocalcemia is a common complication of PTX, caused by the rapid decline in PTH levels after surgery, which leads to shift of calcium from the bloodstream into bones." (PMID 41367906, 2025). "Other studies defined hypocalcemia by determining cut‐off points accompanied by specific conditions (symptomatic patients, abnormal PTH, requiring treatment, duration)." (PMID 40517023, 2025).
Hypocalcemia (continued). "Over the next four weeks, the intact PTH level, which had transiently increased due to hypocalcemia, returned to normal with calcium supplementation." (PMID 41479802, 2025). "Following parathyroidectomy, the hypocalcaemia-related symptoms resolved, and the serum calcium and parathyroid hormone (PTH) levels have returned to normal." (PMID 41473619, 2025). "Postoperative measurement of intact PTH is widely used to assess hypocalcemia after TT, and numerous studies have investigated the optimal time for measurement." (PMID 40786097, 2025). "We found that normal-weight patients with PHPT have higher blood PTH values, higher rates of osteoporosis, and postoperative symptomatic hypocalcemia compared to patients with higher BMI." (PMID 40332255, 2025). "Most commonly, it leads to elevation of PTH, hypocalcemia, and decreased bone mineral density (BMD)." (PMID 40444234, 2025). "As a conclusion, IP significantly affects postoperative serum Calcium and PTH levels and plays important role for postoperative hypocalcemia and hypoparathyroidism." (PMID 40205289, 2025). "Emerging evidence highlights that magnesium depletion is often intertwined with other electrolyte disturbances, such as hypokalemia and hypocalcemia, due to its role in regulating renal potassium excretion and parathyroid hormone (PTH) activity." (PMID 40388464, 2025). "Following parathyroidectomy, the hypocalcaemia-related symptoms resolved, and the serum calcium and PTH levels normalized." (PMID 41473619, 2025). "This led to the suspicion of PHP1A, which was subsequently confirmed at five years of age when laboratory reevaluation revealed hypocalcemia, hyperphosphatemia, and elevated PTH levels." (PMID 40125101, 2025). "Initial laboratory workup revealed severe hypocalcemia, hyperphosphatemia, and markedly low parathyroid hormone levels." (PMID 40070612, 2025). "Relative hypoparathyroidism, though characterized by normal serum PTH and calcium levels, still necessitates treatment due to clinically relevant symptoms or signs of hypocalcaemia." (PMID 41229353, 2025). "The pathophysiology involves accelerated bone remodeling under chronic PTH stimulation, followed by abrupt mineralization and calcium influx into osteoid tissue after rapid postoperative PTH decline, resulting in severe hypocalcemia." (PMID 40979702, 2025). "PTH possesses a crucial role in calcium homoeostasis, by aiming to restore serum calcium levels in the state of hypocalcemia through its renal, intestinal, and bone actions." (PMID 40177730, 2025). "Our case reports the late presentation of PHP in an adult with symptomatic hypocalcemia with elevated PTH levels, hyperphosphatemia, and hypocalciuria, in the absence of classical features of AHO." (PMID 41170251, 2025). "Routine postoperative monitoring of serum calcium and PTH levels is essential for early detection and management of hypocalcemia." (PMID 40710393, 2025). "Disorders of mineral metabolism, such as hyperphosphatemia, hypocalcemia, and elevated levels of parathyroid hormone (PTH), are often seen in patients with CKD." (PMID 40636262, 2025). "HBS results from an abrupt decline in PTH levels, leading to hypocalcemia, hypophosphatemia, and hypomagnesemia." (PMID 41293386, 2025). "The patient with KSS manifested hypocalcemia (serum calcium level of 6.7 mg/dL) and a low PTH level of 3.0 pg/dL, consistent with hypoparathyroidism at 4 years of age." (PMID 40382647, 2025). "Less than half of our cohort has hypocalcemia, and three patients with low PTH levels also had normal calcium levels." (PMID 38591167, 2024). "Synthesis of 1-α-hydroxylase—D3 (or cholecalciferol) increase—is enhanced by PTH and hypocalcemia, while hyperphosphatemia and FGF-23 accelerate D3 degradation." (PMID 38785509, 2024). "In P. falciparum malaria, patients often exhibit hypocalcemia, hypophosphatemia, and low PTH levels, with parathyroid gland failure potentially contributing to these abnormalities." (PMID 39492784, 2024).